ITGA6 (integrin subunit alpha 6)
Description:
Integrin alpha-6/beta-1 (ITGA6:ITGB1) is a receptor for laminin on platelets (By similarity). Integrin alpha-6/beta-1 (ITGA6:ITGB1) is present in oocytes and is involved in sperm-egg fusion (By similarity). Integrin alpha-6/beta-4 (ITGA6:ITGB4) is a receptor for laminin in epithelial cells and it plays a critical structural role in the hemidesmosome (By similarity). ITGA6:ITGB4 binds to NRG1 (via EGF domain) and this binding is essential for NRG1-ERBB signaling. ITGA6:ITGB4 binds to IGF1 and this binding is essential for IGF1 signaling. ITGA6:ITGB4 binds to IGF2 and this binding is essential for IGF2 signaling.
Synonyms: CD49f; VLA-6; ITGA6A; ITGA6B; JEB6
Tractability: Antibody: UniProt places it where antibodies can reach, with high confidence; its Gene Ontology location is reachable by antibodies, with high confidence; UniProt predicts a signal peptide or a membrane-spanning region. PROTAC: ubiquitination databases record sites on it; its protein half-life has been measured.
Target class: Membrane receptor
Gene: Protein-coding gene on chromosome 2 (172,234,216 to 172,506,459, forward strand). Ensembl gene ENSG00000091409.
Subcellular location: Cell membrane
Pathways (Reactome):
Developmental Biology: Developmental Lineage of Mammary Gland Alveolar Cells; Developmental Lineage of Mammary Gland Luminal Epithelial Cells; Developmental Lineage of Mammary Gland Myoepithelial Cells; Developmental Lineage of Mammary Stem Cells; Differentiation of Keratinocytes in Interfollicular Epidermis in Mammalian Skin
Extracellular matrix organization: Assembly of collagen fibrils and other multimeric structures; Integrin cell surface interactions; Laminin interactions; Syndecan interactions
Cell-Cell communication: Type I hemidesmosome assembly
Hemostasis: Basigin interactions
Gene Ontology:
Molecular function: cadherin binding; insulin-like growth factor I binding; neuregulin binding; protein binding; signaling receptor activity
Biological process: cell-matrix adhesion; cell-substrate adhesion; ectodermal cell differentiation; nail development; negative regulation of extrinsic apoptotic signaling pathway; positive regulation of apoptotic process; positive regulation of cell migration; positive regulation of GTPase activity; positive regulation of transcription by RNA polymerase II; skin morphogenesis; cell-cell adhesion; cell-substrate junction assembly; integrin-mediated signaling pathway; leukocyte migration; positive regulation of neuron projection development; cell adhesion
Cellular component: cell surface; focal adhesion; integrin alpha6-beta1 complex; plasma membrane; integrin alpha6-beta4 complex; basal part of cell; basal plasma membrane; basement membrane; basolateral plasma membrane; external side of plasma membrane; hemidesmosome; integrin complex
Genetic constraint (gnomAD): Loss-of-function variants: 36 observed, 91.47 expected, observed/expected ratio (o/e) 0.39, 90% interval 0.3 to 0.52. The upper end of that interval is the gene's LOEUF score, 0.52, which puts it in group 2 of 6, group 1 being the genes least tolerant of losing a copy. Missense variants: 780 observed, 1,005.5 expected, observed/expected ratio (o/e) 0.78, 90% interval 0.73 to 0.82. Synonymous variants: 320 observed, 381.92 expected, observed/expected ratio (o/e) 0.84, 90% interval 0.76 to 0.92.
Homologues: Orthologues: chimpanzee ITGA6 (98% identical), macaque ITGA6 (96% identical), mouse Itga6 (91% identical), dog ITGA6 (91% identical), rat Itga6 (91% identical), pig ITGA6 (91% identical), guinea pig ITGA6 (86% identical), rabbit ITGA6 (79% identical), tropical clawed frog itga6 (65% identical), zebrafish itga6a (61% identical), zebrafish itga6b (56% identical), zebrafish itga6l (44% identical), and 5 more. Paralogues in human: ITGA7 (47% identical), ITGA3 (36% identical), ITGAV (27% identical), ITGA5 (26% identical), ITGA8 (25% identical), ITGA4 (24% identical), ITGA2B (23% identical), ITGA10 (23% identical), ITGA11 (22% identical), ITGA9 (22% identical), ITGA2 (21% identical), ITGA1 (20% identical), and 5 more.
Diseases named in the same sentence as ITGA6 in open-access papers:
ITGA6 is named in the same sentence as 168 diseases in open-access papers, as found by Europe PMC text mining. Sharing a sentence is not in itself a finding about the gene and the disease. The quoted sentences say what the papers report.
breast carcinoma (133 papers, 2008 to 2025). "Cell and context specific changes in ITGA6 expression dictate its role in tumour biology with elevated levels associated with breast cancer, colorectal cancer and leukaemia." (PMID 41222740, 2025). "High Itgα6 levels are associated with poor survival in breast cancer and ITGA6 expression is an independent prognosis factor in ER-negative breast cancer." (PMID 38835038, 2024). "Many integrins contribute to tumor progression, and ITGA6 has been implicated in breast cancer progression." (PMID 34336650, 2021). "In this context, ITGA6 has been linked to cancer stemness and invasiveness in breast cancer through a HIF-dependent mechanism." (PMID 31429720, 2019). "ITGA6, which encodes the breast cancer stem cell marker CD49f, was also modestly increased after fructose adaptation in MCF-7 and MDA-MB-231." (PMID 29796188, 2018). "ITGA6 has two variants: α6A and α6B, with past studies suggesting that the α6A isoform does not maintain tumor stem cell function, while breast cancer cells with high expression of integrin α6Bβ1 exhibit CSC characteristics." (PMID 39239559, 2024). "In addition, it has been suggested that ITGA6+/EpCAM+ mammary luminal progenitor cells were possible transformation targets in basal-like breast cancers, which have close associations with poor prognosis." (PMID 31340763, 2019). "However, no study has determined the relationship between ITGA6 and radiation sensitivity in breast cancer cells, and the molecular mechanism underlying how ITGA6 confers radioresistance to tumor cells remains unclear." (PMID 27624978, 2016). "Taken together, these findings indicate that ITGA6 might be involved in a mechanism that underlies radiation resistance and that ITGA6 could be a potential target for therapies aimed at overcoming radiation resistance in breast cancer." (PMID 27624978, 2016). "Gene expression correlation analysis revealed that USP30 negatively correlates with the expression of stem cell markers such as MMP2, MMP9, MYC, OCT4(POU5F1), NANOG, ALDH1A3, CD133 (PROM1), EPCAM, CD24, and ITGA6 in breast cancer cohorts." (PMID 41306556, 2025). "The clinical relevance of SPDEF methylation is further supported by prior studies using MSRE-qPCR in other cancers (e.g., ITGA6 in breast cancer, DOK7 in gastric cancer)." (PMID 40457266, 2025). "We have chosen to examine the phenotype of induced loss of Itga6 in Blg-Cre;Brca1F/F;Trp53F/F mice, a well-established model of basal-like tumors, mimicking features characteristic of human BRCA1-deficient breast cancer." (PMID 38835038, 2024). "In breast cancer, ITGA6 expression is recognized as a stronger predictor of poor prognosis than other known variables, such as estrogen receptor status." (PMID 37444576, 2023). "Telomerase reverse transcriptase (TERT) has a well-known role in carcinogenesis and, together with ITGA6, is recognized as a stem cell marker in breast cancer cell lines and has been described as having a substantial direct association with malignant tissue." (PMID 37444576, 2023). "Many studies show that ITGA6 is overexpressed in several carcinomas, including breast cancer, colorectal cancer, kidney cancer, and gallbladder carcinoma." (PMID 36268277, 2022). "A previous study has suggested that miR-92a was downregulated in breast cancer cells, and it has been identified that the expression of ITGA6 was increased in cisplatin-resistant SKOV3 and cisplatin-resistant A2780 cells, and also in drug-resistant tissues." (PMID 35168644, 2022). "Public, database-based research revealed that ITGA6 expression is an independent prognostic factor of survival in breast cancer patients." (PMID 33540700, 2021). "At present, there are few research studies on the biological function of ITGA6, among which tumor-related research studies are mainly focused on breast cancer." (PMID 34413286, 2021). "Recently, it has been demonstrated that ITGA6 mediates radio- and chemo-resistance in breast cancer." (PMID 32806777, 2020).
breast carcinoma (continued). "In breast cancer, for example, ITGA6 induced radiation resistance via the PI3K/Akt and MEK/Erk signalling pathways." (PMID 33255413, 2020). "NFATC1 binds to the ITGB3 promoter in osteoclast precursor cells, while NFATC2 and NFAT5 promote ITGA6/ITGB4-mediated cell invasion in breast cancer." (PMID 31730483, 2019). "In a medium cohort of patients in previous studies, these findings revealed that ALDH1A3, PROCR, ITGA6+, ITGA6+/EpCAM− and ITGA6−/EpCAM+ were correlated with reduced RFS or overall survival of these breast cancer patients." (PMID 31340763, 2019). "Some of these markers and combined markers (i.e., CD44+/CD24low ALDH+ and ITGA6+) are considered to correlate with poor prognosis in breast cancer, because they also identified a BCSC subpopulation." (PMID 31340763, 2019). "Larger sample clinical studies are required to verify the clinical significance of ITGA6 as an independent prognostic factors for breast cancer, and an animal experiment requires further study." (PMID 27624978, 2016). "This study provides evidence of potential mechanism of ITGA6 with DNA double strand damage repair via Akt pathway in breast cancer cells." (PMID 27624978, 2016). "The results showed that the protein and mRNA expression levels of ITGA6 was higher in breast cancer cells than in normal cells." (PMID 27624978, 2016). "A search of public databases also revealed that ITGA6 expression is an independent prognostic factor of survival in breast cancer patients." (PMID 27001172, 2016). "Of note, an inverse relationship between ITGA6 mRNA and estrogen receptor (ER) mRNA levels was identified in this study, prior to the discovery that ITGA6 mRNA is a marker of the basal-like breast cancer subtype." (PMID 27001172, 2016). "In summary, this study provides evidence of a mechanism that ITGA6 contributes to radioresistance via an ITGA6/Akt/Erk pathway in breast cancer cells." (PMID 27624978, 2016). "The expression of ITGA6 was examined in human breast cancer and normal breast cell lines using western blot analysis." (PMID 27624978, 2016). "Overexpression of ITGA6 affect processes including cellular anti-apoptosis, cell cycle arrest and DNA double-strand break repair in breast cancer cells." (PMID 27624978, 2016). "We first confirmed using The Cancer Genome Atlas (TCGA) data that ITGA6 expression is enriched in basal-like breast cancers." (PMID 27001172, 2016). "Our results support previous studies describing a positive, direct relationship between ITGA6 levels and metastatic potential using a panel of breast cancer cell lines, including MDA-MB-231 cells." (PMID 27001172, 2016). "ITGA6 protectived responses to radiotherapy in breast cancer cells by altering cell apoptosis, DNA damage repair and cell-cycle regulation." (PMID 27624978, 2016). "We also explored the role of ITGA6 in the regulation of radiation sensitivity in breast cancer using the colony formation assays, cell cycle analyses, apoptosis assays and immunofluorescence analyses." (PMID 27624978, 2016). "Moreover, BORG:TRIM28 complexes also govern the self-renewal and expansion of breast cancer stem cells, doing so by inducing the expression of Nanog, Aldh1a3, and Itga6/α6 integrins." (PMID 39335212, 2024). "Additionally, ITGA6 overexpression promotes radioresistance in breast cancer cells by activating the PI3K/Akt pathway." (PMID 38493128, 2024). "Interestingly, ITGA6 levels were significantly higher in basal-like tumors when compared with the other breast cancer subtypes, while ITGA3 levels were lower in this group." (PMID 38835038, 2024). "HIF signaling also controls the invasion of metastatic breast cancer cells via upregulating ITGA6." (PMID 37444576, 2023). "The adjuvant radiation for breast cancer that targets ITGA6 signaling might be a beneficial strategy." (PMID 37444576, 2023).
breast carcinoma (continued). "Differentially expressed genes, especially those in five modules, including OAS1, IFI27, LPAR1, PTGFR, ITGB4, and ITGA6, might participate in the epithelial-mesenchymal transition process in breast cancer cell line DKTA." (PMID 36289533, 2022). "We previously determined that the aryl hydrocarbon receptor (AhR) agonist aminoflavone (AF) inhibits the expression of the CSC biomarker α6-integrin (ITGA6) to disrupt the formation of luminal (hormone receptor-positive) mammospheres (3D breast cancer spheroids)." (PMID 35694715, 2022). "In addition our study further confirmed that high levels of FOXD1, ITGA6 and SERPINE1 were associated with HER2-overexpressing breast cancer cells resistant to trastuzumab and they were regulated by acetylation of H3K27 and H3K18." (PMID 30914750, 2019). "The relationship between high levels of HIFα protein and increased expression of HIF transcriptional targets, including ITGA6, in basal breast cancers likely directly contributes to their enhanced aggressive nature, including the enhanced risk of relapse within the first five years of diagnosis." (PMID 27001172, 2016). "Targeting ITGA6 signaling might be an effective strategy for using adjuvant radiotherapy in breast cancer." (PMID 27624978, 2016). "In addition, compared to ionizing radiation alone, treatment with LY294002 resulted in significantly higher levels of radiosensitivity in breast cancer cells, and the radioresistance induced by ITGA6 overexpression was restored by inhibiting PI3K/Akt." (PMID 27624978, 2016). "We then sought to determine whether ITGA6 modulates radiosensitivity in breast cancer cells via a mechanism involving Akt and Erk signaling." (PMID 27624978, 2016). "Breast cancers have been classified into five major subtypes on the basis of global gene expression; one of several genes up-regulated in basal-like cancers relative to other subtypes is ITGA6." (PMID 27001172, 2016). "ITGA6 serving as “functional” markers for mammary cancer stem cells also may be one of potential mechanism of ITGA6 contributes to DNA double strand damage repair." (PMID 27624978, 2016). "ITGA6 expression has previously been shown to predict poor outcome in breast cancer." (PMID 22112299, 2011). "Indeed, aberrant expression of BORG in mouse and human breast cancers was associated with the acquisition of breast cancer stem cell-like properties and upregulation of known breast cancer stem cell markers, such as NANOG, ALDH1, and ITGA6/α6Integrin/CD49f." (PMID 39335212, 2024). "Moreover, ITGA6 could mediate radiation resistance of breast cancer through activating Akt/ERK signaling pathway." (PMID 34413286, 2021). "Similarly, we observed an increase in the expression of Itgb1 (coding for CD29) and Itga6 (coding for CD49f), together with the upregulation of genes associated with EMT, a key biological process also known to modulate the stemness of breast cancer cells." (PMID 32581213, 2020). "However, the role that the ITGA6-associated signaling network plays in radiosensitivity in breast cancer has not been described." (PMID 27624978, 2016). "The upregulated differentially expressed breast cancer stem cell markers included CD56/NCAM1, POU5F1, PROCR/CD201, ITGA6, and the downregulated were ESR1, PGR, HER2/ERBB2, ABCG2, CD44, CD24, EPCAM, and CDH1." (PMID 40690373, 2025). "Studies have found that in breast cancer cells, the AhR agonist Aminoflavone pro-drug (AFP464) can inhibit the formation of breast tumor spheres and suppress TIC growth by inhibiting ITGA6 expression in breast cancer." (PMID 39239559, 2024). "To study their role in tumorigenesis, we first interrogated the TCGA database comprising the main molecular subtypes of breast cancer, for the expression of ITGA3 and ITGA6 transcripts." (PMID 38835038, 2024). "It has been demonstrated that the upregulation of ITGA6 coding for integrin alpha 6 by HIF modulates stem cell-like features and invasion of MDA-MB-231 breast cancer cells." (PMID 36139678, 2022).